ALB (albumin)
Diseases named in the same sentence as ALB in open-access papers (continued):
Sharing a sentence is not in itself a finding about the gene and the disease.
fibrosis (125 papers, 2007 to 2026). the formation of excess fibrous connective tissue in an organ or tissue in a reparative or reactive process. "On the other hand, each fibrosis group was associated with a drop in the levels of both albumin and platelet count in case of co-infection compared to HCV mono-infection but the difference was statistically not significant." (PMID 35080677, 2022). "Three of the five variables (bilirubin, variceal bleeding, albumin) are associated with advanced fibrosis and only a 4-year mortality risk is calculated." (PMID 34640494, 2021). "T2DM was independently associated with fibrosis progression (HR 1.88, 95% CI 1.40–25.2, P<0.001) as well as age ≥50 years and serum albumin concentration <4.2 g/dL." (PMID 33186403, 2020). "The elevated serum OPN level was an independent risk factor in estimating significant (F≥2) fibrosis in a model combining alkaline phosphatase, albumin, hemoglobin, OPN and FibroMeter® levels." (PMID 22530059, 2012). "With the strong association between several key parameters (Fibrosis, HBsAg, ALB, HBcAb) and the extent of NK-cell cytokine activity in the model, we then generated a nomogram that can be used to calculate the predicted likelihood of an NK-cell-produced cytokine response in an individual patient." (PMID 28725030, 2017). "Ligilactobacillus was positively correlated with liver function, fibrosis, and the coefficient, and negatively correlated with intestinal barrier integrity and ALB levels." (PMID 40552147, 2025). "Albumin levels remained unchanged at Week 8 but significantly increased in both groups by Week 10 (p < 0.05) compared to the fibrosis group." (PMID 40586605, 2025). "We next sought other signs of uveitis in Yap cKO eyes, such as a breakdown of the blood-aqueous barrier (BaB), which results in exudation of blood components like albumin and which is usually accompanied by fibrosis." (PMID 38272861, 2024). "Specifically, platelets and albumin levels markedly increased in the advanced fibrosis group (165 × 103/μL at baseline to 193 × 103/μL at Week 48; P < 0.001) and the low‐albumin group (3.9 g/dL at baseline to 4.2 g/dL at Week 48; P < 0.01)." (PMID 38572327, 2024). "Serum bilirubin and albumin levels, used as markers of hepatic synthetic function, were similar in the advanced fibrosis and low-grade fibrosis groups." (PMID 39131712, 2024). "The patients with fibrosis were significantly older and their levels of albumin, AST, ALT, creatinine, and INR were significantly higher." (PMID 37374233, 2023). "The group of patients with fibrosis was older (p = 0.02) and had higher values for albumin (p = 0.007), AST (p = 0.002), ALT (p = 0.001), creatinine (p < 0.001), INR (p = 0.02), and uric acid (p < 0.001) compared to the group with no fibrosis." (PMID 37374233, 2023). "There were no statistical differences in other serological parameters between the groups, except the level of albumin, which significantly decreased in the fibrosis group (SF, AF group) compared with the NF group." (PMID 35668948, 2022). "The results showed that QYDP treatment reduced serum creatinine, blood urea nitrogen, and 24-h urinary albumin and improved kidney histology and fibrosis." (PMID 33679423, 2020). "According to the results, tanshinone IIA reduces liver fiber scores, collagen content in liver tissue, multiple serum fibrosis indexes, and serum liver enzyme levels and restores the serum albumin levels." (PMID 31915451, 2019). "There was no significant linear correlation between mK/mP and eGFR, age, body mass index, plasmatic albumin, biopsy mass, tubular atrophy, fibrosis percentage, mT120/mT60 ratio, and meropenem plasmatic levels at T1, T2, T3, T60, and T120." (PMID 31828087, 2019). "Liver cell impairments suggested that the synthesis of albumin (ALB) was significantly impaired in the rat fibrosis models (P < 0.5)." (PMID 33817199, 2019). "Patients with F3-4 fibrosis tended to be older, had lower albumin and platelets, higher bilirubin, ALP and AST." (PMID 30120271, 2018).
fibrosis (continued). "Parameters of age, ALT, AST, ALP, GGT, Total bilitubin, hyaluronic acid, laminin, PIIINP and CO-IV were positively, and platelet count, albumin, Lg HBVDNA, lg HBsAg were negatively associated with fibrosis stages." (PMID 27605044, 2017). "When individuals with steatohepatitis with fibrosis are considered, the albumin values found were even lower and just below the normality value recommended (3.4 g/dL)." (PMID 26120587, 2015). "The following liver function parameters were worse in NAFLD patients with advanced fibrosis: albumin (P = 0.016); platelet count (P < 0.001); and prothrombin time (P < 0.001)." (PMID 27785221, 2013). "The hemoglobin, albumin, lymphocyte, and platelet score was significantly and negatively correlated with C-reactive protein, aspartate, alanine transaminase, gamma glutamyl transferase, aspartate to platelet ratio index, and Fibrosis-4 values." (PMID 38294124, 2024). "In addition, in the HBV-infected group, the serum AST, Dbil, HA, and ALB concentrations in patients with hepatitis and fibrosis were significantly different compared to those in patients with hepatitis (P < 0.05)." (PMID 35646962, 2022). "It has been reported that patients with LC who achieve SVRs with DAA therapy show improvements in liver function and fibrosis, with improvements in aspartate transaminase levels, alanine transaminase levels, serum albumin levels, type IV collagen levels, and the fibrosis-4 index." (PMID 36013545, 2022). "Furthermore, the expression of human albumin cells was higher in the cirrhotic transplanted group than in the mild fibrosis transplanted group and more in the macrophage-depleted groups than in the nondepleted groups." (PMID 30631109, 2019). "Albumin levels were significantly lower in individuals with steatohepatitis with fibrosis." (PMID 28685131, 2017). "In contrast, none of the other parameters in routine clinical use were significantly correlated to the percentage of fibrosis: eGFR (Rho = −0.222, P = 0.16), urine albumin-to-creatinine ratio (Rho = −0.137, P = 0.39) and urine protein-to-creatinine ratio (Rho = −0.070, P = 0.66)." (PMID 29208969, 2017). "In addition, the serum level of albumin in the hPMSC-treated group was higher than that in the untreated fibrosis group and approached the normal level of the saline control group at 12 weeks after transplantation." (PMID 28491093, 2017). "Four clinical parameters (Fibrosis value, HBsAg, HBcAb, ALB) were selected in the final model." (PMID 28725030, 2017). "Albumin dosages were significantly lower in individuals with steatohepatitis with fibrosis." (PMID 26120587, 2015). "Seven individual protein spots were identified as either significantly increased (α2-macroglobulin, haptoglobin, albumin) or decreased (complement C-4, serum retinol binding protein, apolipoprotein A-1, and two isoforms of apolipoprotein A-IV) with advanced fibrosis." (PMID 17625010, 2007). "It covers a range of variables such as age, liver biochemical markers (ALT, AST, Albumin, GGT, T.Bil), metabolic indicators (BMI, HbA1C, FBS, TG, TC, LDL, HDL), and markers of liver health or disease (AFP, PLTs, Fibrosis Stages, Sonography)." (PMID 41026784, 2025). "Compared with the fibrosis group, biochemical parameters of liver function, including ALT and AST levels were reduced, while the ALB levels increased in all hPMSC treatment groups, especially in the TM groups." (PMID 34016164, 2021). "NAFLD fibrosis score (NFS) is calculated based on following measurements: age, BMI, glucose blood concentration, platelet count, albumin serum level and AST/ALT ratio." (PMID 34945016, 2021). "We examined the colocalization of FN-EDA with albumin (hepatocyte marker), CD31 (endothelial marker), and α-SMA (activated HSC marker) in mouse fibrosis hepatic tissues." (PMID 33293521, 2020). "A similar score, called the Delta Fibrosis score, utilized GGT, age, albumin, and serum cholinesterase, and had an AUROC of 0.87 in a cohort of 100 HDV positive patients." (PMID 33052263, 2020).
fibrosis (continued). "Consistent with the albumin data, significantly lower levels of the serum AST and ALT were resulted from the addition of kallistatin compared to the fibrosis model group." (PMID 24558397, 2014). "Additionally, compared to the suspected fibrosis subgroup, the advanced fibrosis subgroup had elevated levels of FPG, HbA1c, and SIRI (P< 0.05), while Hb, PLT, and ALB levels were significantly lower (P< 0.05)." (PMID 40265164, 2025). "NAFLD fibrosis score (NFS), using a combination of the parameters of age, fasting glucose, body mass index (BMI), platelet count, albumin, and AST/ALT ratio, as well as fibrosis-4 index (FIB-4), including age, AST, ALT, and platelet count, are among the most widely used noninvasive tests." (PMID 37626604, 2023). "Therefore, we looked at albuminuria (albumin to creatinine ratio—ACR), injury score, fibrosis, and kidney weight." (PMID 38055691, 2023). "The mean blood albumin levels of the subjects without NAFLD or advancing fibrosis were considerably greater than those of the individuals with these conditions." (PMID 37111111, 2023). "The mean albumin in those without advanced fibrosis was significantly higher than in those with advanced fibrosis." (PMID 37111111, 2023). "The NAFLD-fibrosis score incorporates the patient's age, body mass index, and the presence or absence of impaired fasting glucose and albumin to the predictors of the FIB-4 score." (PMID 37265583, 2023). "The final model (R-fibrosis) included GGT/PLT, ALB and A/G in addition to R-score." (PMID 35347597, 2022). "Serum albumin, AST, and ALT decreased the most in patients with NASH and NASH plus fibrosis." (PMID 28919979, 2017). "In our study, serum albumin levels were lower in the group with steatohepatitis without fibrosis versus the steatosis group but still within the normality range." (PMID 26120587, 2015). "Laboratory parameters such as ALT, albumin, prothrombin time, international normalized ratio levels and the AST/platelet ratio index score were analysed for dependence with the modified Ishak HAI fibrosis groups." (PMID 18638013, 2008). "Significant differences in transaminases (p > .05), albumin (p < .009), cholesterol (p0.03), low density lipoproteins (LDL) (0.006), triglycerides (p < .001), HSI (p < .001), FIB4 (p < .001) and APRI (p < .001) were reported in those with significant than early fibrosis and control groups." (PMID 36444680, 2023). "Here, we show that Albumin-CRE-driven TFEB overexpression in the liver of transgenic mice results in a severe phenotype characterized by a progressive increase in liver mass, hyperplasia of bile ducts, altered biliary tree structure, multifocal biliary cystic hyperplasia, and fibrosis." (PMID 32424153, 2020). "However, negative correlations were found between fibrosis stage and albumin, CHE, PLT, and CP (all P-values<0.05)." (PMID 24282481, 2013). "Analysis of cohort B showed higher levels of hsCRP (median 10.07 vs. 7.02 mg/L; p < 0.0004) and lower levels of albumin (median 31.4 vs. 25.87 g/L; p = 0.0012) in MF versus MPN without fibrosis and/or the healthy controls." (PMID 36900271, 2023). "In the chronic hepatitis C group with significant fibrosis (CHC-SF), albumin and platelet (PLT) levels were significantly lower in comparison with the chronic hepatitis C group with non-significant fibrosis (CHC-NSF), NASH and CG." (PMID 37569857, 2023).
cerebrovascular disease (118 papers, 2005 to 2025). "Lower albumin levels and body mass index are associated with an increase in adverse outcomes such as cardiovascular and cerebrovascular disease, hospitalization, and infection." (PMID 40824912, 2025). "Serum albumin concentration is a simple and inexpensive routine laboratory test that provides relevant risk information for patients with certain cerebrovascular diseases." (PMID 37210474, 2023). "Albumin is the strongest indicator of most causes of death, especially for cerebrovascular disease (CVE), peripheral vascular disease (PVD) and gastrointestinal (GI) disease, according to the heatmap generated by AICare." (PMID 38106617, 2023). "Research results in recent years had shown that the red cell distribution width (RDW) levels of blood and human serum albumin (ALB) are both predictors of the mortality risk of cerebrovascular disease." (PMID 36567762, 2022). "Age, intravenous hormone usage, hemoglobin, platelet, international normalized ratio, urea nitrogen, creatinine, estimated Glomerular Filtration Rate, albumin, complications with viral hepatitis and cardio-cerebrovascular disease were significant factors associated with UGIB." (PMID 35879668, 2022). "However, in patients who experienced CV death, multivariate regression showed that a history of CV and cerebrovascular disease, albumin level, and uric acid level were independent risk factors for CV death." (PMID 32223483, 2020). "The multivariable logistic regression analysis incorporated these predictors, with age, history of cerebrovascular disease, ASA classification, albumin level, and surgical approach recognized as independent risk factors for POD." (PMID 38777824, 2024). "Generally, increased serum total protein and albumin content indicates enhanced liver protein synthesis, and the triglyceride metabolism level is related to cardiovascular and cerebrovascular diseases." (PMID 38886454, 2024). "Albumin (ALB), a marker of human nutritional status, has been extensively utilized in prognostic studies of cerebrovascular disease." (PMID 39839876, 2024). "Regarding AoAC, older age, cerebrovascular disease, decreased albumin, increased Kt/V, and the use of antiplatelet agents were associated with an increase in AoAC." (PMID 34442433, 2021). "Significant differences between groups were found with respect to age, history of cerebrovascular disease, serum protein, serum albumin level, hemoglobin, serum creatinine and eGFR." (PMID 31626671, 2019). "In the multivariate forward analysis, cerebrovascular disease, low albumin, high fasting glucose, high hemoglobin, high CaXP product and low LF (hazard ratios, 0.875; 95% CI, 0.814−0.941; p < 0.001) were independently associated with increased hospitalization." (PMID 29492233, 2018). "In multivariable analysis, independent associates of a baseline LEA in FDS1 were a history of vascular bypass surgery or revascularisation, urinary albumin:creatinine ratio, peripheral sensory neuropathy and cerebrovascular disease (P ≤ 0.035)." (PMID 26684912, 2015). "There were significant associations between patient death and older age, female sex, past history of cerebrovascular disease and lower serum albumin at the time of cardiac assessment." (PMID 25505546, 2014). "Furthermore, albumin levels are also closely related to cardiovascular and cerebrovascular diseases." (PMID 40606134, 2025). "Some circulating immune inflammatory cells, serum albumin, body mass index (BMI) and other indicators reflecting the inflammation and nutritional status of the body are closely related to the prognosis of cardio-cerebrovascular diseases." (PMID 39726875, 2024). "Univariate Cox proportional hazards analysis revealed that clinical and laboratory findings such as age, history of DM, CAD, cerebrovascular disease, arrhythmia, serum albumin and NT-proBNP levels, and 24-hour urine volume were significantly associated with CV events." (PMID 25739020, 2015).
cerebrovascular disease (continued). "Furthermore, C-reactive protein, albumin and neutrophils were confirmed to have independent prognostic value in patients dying of cancer as well as cardiovascular and cerebrovascular disease." (PMID 25730322, 2015). "Cerebrovascular disease, respiratory complications, WBC count, albumin concentration, CRP concentration, and mGPS were detected as predictive factors of PAP." (PMID 41239633, 2025). "The blood urea nitrogen to albumin ratio (BAR) has emerged as a potential prognostic biomarker in elderly patients with cardiovascular and cerebrovascular diseases (CVDs)." (PMID 41144534, 2025). "Multivariate analysis of the training set revealed that factors including age, history of cerebrovascular disease, American Society of Anesthesiologists (ASA) classification, albumin level, and surgical approach had significant effects on POD." (PMID 38777824, 2024). "In older patients with HCC, factors such as age, cerebrovascular disease history, ASA classification, albumin levels, and the type of surgical procedure are identified as independent predictors of POD." (PMID 38777824, 2024). "CVA: Cerebrovascular disease; CVD: Cardiovascular disease & cardiac interventions; PVD: Peripheral vascular disease; eGFR: estimated glomerular filtration rate; ACR: Albumin to creatinine ratio." (PMID 33364086, 2020). "In multiple logistic regression analysis, independent associates of a baseline LEA in FDS1 were a history of vascular bypass surgery or revascularisation, urinary albumin:creatinine ratio, PSN and cerebrovascular disease." (PMID 26684912, 2015). "One of the main strengths is the use of a large, diverse cohort, which enhances the generalisability of our findings regarding the prognostic value of the Blood Urea Nitrogen to Albumin Ratio (BAR) in elderly patients with cardiovascular and cerebrovascular disease." (PMID 41144534, 2025). "Our data for major lethal diseases (cardiovascular and cerebrovascular diseases, COPD and cancer) suggest that the initial stage and end stage of this continuous process were similar because of changes in levels of the four indicators (RBC count as well as levels of ALB, CRE and AST)." (PMID 32689964, 2020).